TNF (tumor necrosis factor)
Diseases named in the same sentence as TNF in open-access papers (continued):
Sharing a sentence is not in itself a finding about the gene and the disease.
rheumatoid arthritis (continued). "Patients with EO-rheumatoid arthritis (EO-RA) have higher serum interleukin-6 levels and lower serum TNFα levels than patients with NEO-RA, and high levels of TNFα are associated with higher risk of hospitalization and death." (PMID 35351986, 2022). "We have further noted a correlation between osteoporosis markers in the blood of rheumatoid arthritis (RA) patients, polymorphisms in the TNF-α gene and those of its receptor, and MAP infection." (PMID 35444957, 2022). "The use of TNF blockers in patients with rheumatoid arthritis (RA) and psoriasis is associated with a lower risk of AD." (PMID 36428505, 2022). "A recent study addressing the increased risk of AD in patients affected by rheumatoid arthritis (RA) indicates that RA patients treated with anti-TNFα therapy for RA showed a reduced risk to develop AD." (PMID 35769472, 2022). "Indeed, effective anti-TNF therapy has been linked to these processes in other chronic inflammatory diseases outside of the gastrointestinal tract, e.g., rheumatoid arthritis, psoriatic arthritis, and ankylosing spondylitis, yet this association is less clear in IBD." (PMID 36153599, 2022). "Rheumatoid arthritis (RA), administration of tumor necrosis factor (TNF) alpha inhibitors, and underlying malignancies have all been associated with FVIII autoantibody formation." (PMID 34347197, 2021). "Loss of TNFα signaling control has been shown to contribute to numerous diseases, including rheumatoid arthritis (RA), Crohn's disease, atherosclerosis, cancer, and other autoimmune diseases." (PMID 33776573, 2021). "Anti-TNF-α drugs are effective in the treatment of inflammation associated with a variety of autoimmune diseases, such as rheumatoid arthritis (RA), inflammatory bowel disease (IBD), ankylosing spondylitis, and Behcet’s disease." (PMID 34367136, 2021). "Immunogenicity related to treatment with TNF inhibitors (TNFi) is one of the causes for the decreased attainment of clinical response in patients with rheumatoid arthritis (RA)." (PMID 34079038, 2021). "MAPKAPK2 deficient animals display significant attenuation of TNF-α production in response to LPS, resistance to the development of rheumatoid arthritis (RA), and a reduction in atherosclerotic lesion formation." (PMID 34445361, 2021). "Considering the high levels of TNFα in a number of inflammatory diseases such as rheumatoid arthritis suggests that the mechanism underlying the neutrophil priming process and its consequences both in vitro and in vivo may offer new opportunities for therapeutic intervention in pathologic settings." (PMID 33040403, 2021). "Hence, targeting LPS/TNF-α-induced osteoclastogenesis could be a promising therapeutic strategy to inhibit inflammatory bone loss in osteolytic diseases such as periodontitis, rheumatoid arthritis, and osteoporosis." (PMID 33765924, 2021). "In multiple studies conducted in rheumatoid arthritis (RA) patients, the TNF blocking strategy has been associated with an increase of biological markers indicating bone formation and a decrease of those illustrating bone resorption." (PMID 34010320, 2021). "Treatment of mice with an FDA-approved TNFα inhibitor increased survival but prolonged and exacerbated lung pathology, raising concerns for the risk of severe influenza in patients prescribed TNFα-blocking drugs commonly used to treat rheumatoid arthritis, irritable bowel syndrome, and psoriasis." (PMID 33680987, 2021). "Increased evidence indicates an elevated TB risk in patients with rheumatoid arthritis (RA); the risk is even higher for those receiving anti-tumor necrosis factor alpha (TNF-α) therapy." (PMID 31992621, 2020). "This study sought to evaluate the association of 28 single nucleotide polymorphisms (SNPs) within NFKB and inflammasome pathway genes with the risk of rheumatoid arthritis (RA) and response to TNF inhibitors (TNFi)." (PMID 32152480, 2020).
rheumatoid arthritis (continued). "The resounding success of the anti-TNF and anti-IL-6 therapies for conditions such as Rheumatoid arthritis (RA) and SLE, respectively, has caused renewed interest in understanding how, why and when these potent molecules are secreted in health and disease." (PMID 30761138, 2019). "TNF is a major mediator of apoptosis, as well as inflammation and immunity, and it is implicated in the pathogenesis of a wide spectrum of human diseases including sepsis, diabetes, cancer, osteoporosis, multiple sclerosis, rheumatoid arthritis, and inflammatory bowel diseases." (PMID 31331100, 2019). "The immunoregulatory cytokine tumor necrosis factor (TNF)-α plays a key role at all stages of the pathogenic process of rheumatoid arthritis (RA)." (PMID 31906244, 2019). "Indeed therapeutic blockade of the IL-1R via subcutaneous administration of a recombinant IL-1Ra—anakinra (Kineret®)—is licensed for the treatment of rheumatoid arthritis (RA) in patients who fail to respond to anti-TNF and in individuals afflicted by cryopyrin-associated periodic syndromes (CAPS)." (PMID 31231388, 2019). "Given that proinflammatory cytokines, such as TNF-α, IL-6, and IL-17A are crucial inflammatory mediators in synovitis and subsequent tissue damage in rheumatoid arthritis (RA), gut dysbiosis has been implicated in the pathogenesis of RA." (PMID 31652955, 2019). "Our results define a critical role for mTOR in the regulation of the pro-inflammatory response in FLSs and unfold its pathogenic involvement in TNF-driven diseases, such as rheumatoid arthritis (RA)." (PMID 29768212, 2018). "Excessive TNF activity contributes to the complex pathogenesis of rheumatoid arthritis (RA), associated with a pro-inflammatory cascade that includes the production of IL-1 and IL-6, and drives tissue destruction." (PMID 28824652, 2017). "In this regard, the plasma levels of MCP-1, IL-6, and TNF-α could be used as surrogate biomarkers in clinical trials evaluating autoimmune disorders that are associated with elevated levels of these cytokines, such as rheumatoid arthritis and psoriasis." (PMID 28546852, 2017). "A large prospective cohort of 3,266 rheumatoid arthritis (RA) patients on anti-TNF therapy found an increased risk of herpes zoster infection in RA patients, and the severity of many of these cases required hospitalization." (PMID 27092286, 2016). "For example, TNF-α inhibition and IL-1β inhibition have been successful as therapies for rheumatoid arthritis (RA) and chronic inflammatory pathologies associated with cancer, respectively." (PMID 26633296, 2015). "In rheumatoid arthritis (RA), the overproduction of tumor necrosis factor-α (TNF-α) in the inflammatory joints results in local bone loss, which is due to the reduction in osteoblast differentiation." (PMID 25816130, 2015). "Treatment with tumor necrosis factor inhibitors (TNFi) in patients with rheumatoid arthritis (RA) increases the risk of certain cancers." (PMID 26599370, 2015). "This meta-analysis was conducted to investigate whether the status of rheumatoid factor (RF) and anti-cyclic citrullinated peptide (anti-CCP) antibody are associated with the clinical response to anti-tumor necrosis factor (TNF) alpha treatment in rheumatoid arthritis (RA)." (PMID 24586782, 2014). "In addition, the involvement of TNF-α in the bone remodeling imbalance is observed in inflammatory joint diseases including rheumatoid arthritis and ankylosing spondylitis, which are associated with bone destruction and ectopic calcified matrix formation, respectively." (PMID 24592264, 2014). "We previously reported that anti-TNFα therapy given in patients with rheumatoid arthritis (RA) or spondyloarthritis is associated with a significant increase in body weight, BMI, fat mass, and especially fat mass in the android region." (PMID 25161652, 2014).
rheumatoid arthritis (continued). "TNF-α is a pleiotropic cytokine that not only is involved in the growth, differentiation, and cell death of many cell types but also is implicated in pathophysiological conditions including rheumatoid arthritis, inflammatory bowel disease, atherosclerosis, and viral hepatitis." (PMID 25472474, 2014). "Activation of the α7 nAChR expressed on resident macrophages may suppress the local inflammation by reducing the production of pro-inflammatory cytokines TNF and IL-6, which are closely associated with some inflammatory diseases, including sepsis, rheumatoid arthritis, asthma, and diabetes." (PMID 23840548, 2013). "TNF is a pleiotrophic cytokine for the innate immune response and implicated in the mechanisms of several inflammatory diseases, such as chronic asthma, inflammatory bowel disease, and rheumatoid arthritis, and it is produced mainly by activated macrophages in various tissues." (PMID 23094102, 2012). "Several rheumatoid arthritis (RA) susceptibility variants map close to genes involved in the tumor necrosis factor (TNF) signaling pathway, prompting the investigation of RA susceptibility variants in studies of predictors of response to TNF blockade." (PMID 21952740, 2012). "We aimed to investigate insertions and deletions (INDELS) associated with response to TNFα inhibitors in patients with rheumatoid arthritis (RA)." (PMID 22685579, 2012). "Perspectively, understanding the precise molecular mechanism underlying 14.7K-mediated apoptosis blockade could be exploited as a therapeutic strategy for treatment of disorders associated with increased TNF-levels such as rheumatoid arthritis and Crohn’s disease." (PMID 22675546, 2012). "An association between some TNF-α SNPs and adult rheumatoid arthritis (RA) susceptibility, severity and clinical response to anti-TNF-α treatment has been reported." (PMID 23133455, 2012). "Recent studies reported an increased risk of HZ in patients with rheumatoid arthritis (RA) that is attributable both to the disease and to treatment with anti-tumor necrosis factor alpha (anti-TNF) therapies and other immunosuppressive agents." (PMID 22024532, 2011). "Most notably, aberrant expression of the TNFα gene is associated with rheumatoid arthritis (RA) in both humans and animal models." (PMID 18070349, 2007). "In chronic inflammatory diseases, such as rheumatoid arthritis, inflammation acts as an independent cardiovascular risk factor and the use of anti-inflammatory drugs, such as anti-tumor necrosis factor alpha (anti-TNFα), may decrease this risk." (PMID 17335569, 2007). "Inappropriate production of TNF has been implicated in the pathogenesis of a variety of human diseases, including sepsis, cerebral malaria, diabetes, cancer, osteoporosis, allograft rejection, multiple sclerosis, rheumatoid arthritis, and inflammatory bowel diseases." (PMID 17205112, 2006). "The journal retracts the article titled, "Rheumatoid Arthritis-Associated MicroRNA-155 Targets SOCS1 and Upregulates TNF-α and IL-1β in PBMCs" [...]." (PMID 42007900, 2026). "Synovial fibroblasts from individuals with rheumatoid arthritis (RASF) contain a membrane-bound form TNFα." (PMID 41601700, 2026). "In patients who used used anti-TNF agents and developed TB, disease distribution was as follows: ankylosing spondylitis 23 (48.9%), rheumatoid arthritis 13 (27.7%), Behçet’s syndrome 8 (17%) and psoriatic arthritis 3 (6.4%)." (PMID 40307303, 2025). "In patients with rheumatoid arthritis, inflammatory cytokines (tumor necrosis factor-α and interleukin-6) and C-reactive protein have been shown to be positively correlated with the insulin resistance index (homeostasis model assessment)." (PMID 41464548, 2025). "A related study then showed that TNFα inhibition with infliximab reduced 24 h ambulatory blood pressure in rheumatoid arthritis patients." (PMID 40329016, 2025).
rheumatoid arthritis (continued). "mAbs such as infliximab, etanercept, adalimumab, and certolizumab are anti-TNF-α agents used to treat Crohn’s disease, rheumatoid arthritis, and plaque psoriasis." (PMID 40338229, 2025). "Like TNF-alpha, MCP-1 is also associated with the pathogenesis of numerous disease conditions such as metabolic, neuroinflammatory diseases, rheumatoid arthritis and cardiovascular diseases." (PMID 41141269, 2025). "TNF-α is a well-established key mediator of inflammatory pain and plays a crucial role in chronic inflammatory diseases such as rheumatoid arthritis, where TNF-α inhibitors are widely used as effective treatments." (PMID 41009486, 2025). "Previous studies reporting serological analysis of inflammatory bowel disease and rheumatoid arthritis patients who received infliximab, an anti-TNF drug, suggested that infliximab attenuates the immunogenicity of vaccines in these patients." (PMID 41429777, 2025). "In ankylosing spondylitis IL-32γ was elevated in the synovial fluid and in rheumatoid arthritis IL-32 was raised in synovial biopsies, correlating with pro-inflammatory cytokine levels and decreased with anti-TNFα therapy." (PMID 40977709, 2025). "Tumor necrosis factor-alpha (TNF-α) inhibitors are effective treatments for IMIDs such rheumatoid arthritis, psoriatic arthritis, juvenile idiopathic arthritis, ulcerative colitis, psoriasis, Crohn’s disease and ankylosing spondylitis." (PMID 40371340, 2025). "For example, Rituximab is a mAb which targets CD20+ B-cells and leads to B-cell depletion in MS patients, while TNF-α (tumor necrosis factor-α) inhibitor, Infliximab, is used in Rheumatoid Arthritis (RA) and Crohn’s disease." (PMID 40755780, 2025). "B cell depletion confers moderate clinical effectiveness in treating rheumatoid arthritis, whereas anti–TNF-α clearly worsens MS immunopathogenesis." (PMID 40067358, 2025). "In Mac_mt-Co1, IL-17 signaling, ferroptosis, TNF signaling, rheumatoid arthritis, and PI3K–AKT pathways were significantly activated (p < 0.05)." (PMID 41459160, 2025). "Using human and murine models of TNF-α–driven diseases, including myeloproliferative neoplasms and rheumatoid arthritis, we found that TNF-α downregulates syntaxin 17 (STX17), a key mediator of autophagosome-lysosome fusion." (PMID 40493419, 2025). "It has been suggested for the management of inflammation and joint pain and is an antagonist of TNF-α in animal models affected by rheumatoid arthritis." (PMID 39859264, 2025). "In patients with rheumatoid arthritis, bortezomib suppresses the release of pro-inflammatory cytokines TNFα and IL-1β." (PMID 41035952, 2025). "TNF is a pleiotropic cytokine involved in a variety of inflammatory and autoimmune diseases, such as rheumatoid arthritis (RA), psoriasis, Alzheimer’s disease (AD) and multiple sclerosis (MS)." (PMID 41333471, 2025). "Mechanistically, IL-17 acts on synovial fibroblasts and stromal cells, induces RANKL and matrix metalloproteinases, and cooperates with TNF and IL-6, which accelerates bone erosion and cartilage damage in rheumatoid arthritis." (PMID 41303386, 2025). "Rheumatoid arthritis leads to the abundant presence of inflammatory factors such as interleukin(IL)-1,IL-6 and tumor necrosis factor (TNF) in the systemic circulation." (PMID 40496851, 2025). "An increased risk of VTEs was also observed in the ORAL Surveillance study, a randomized, noninferiority, postmarketing phase IV safety study comparing tofacitinib with anti-tumor necrosis factor in patients with rheumatoid arthritis." (PMID 39980606, 2025). "The elevated secretion of IL-17 A and TNF-α aligns with the increased prevalence of autoimmune disorders such as rheumatoid arthritis, lupus erythematosus, and multiple sclerosis in women." (PMID 41194200, 2025). "The Ke0 value of TNF-α for PTD was 3.4 × 10−4, suggesting a moderate delay in modulating TNF-α, implicating TNF-α as a primary target for PTD’s anti-rheumatoid arthritis effects in vivo." (PMID 40332334, 2025).
rheumatoid arthritis (continued). "Supporting this interpretation, WBC has been shown to reduce tumor necrosis factor-α (TNF-α) levels in rheumatoid arthritis patients, and TNF-α in turn promotes the release of calprotectin." (PMID 41226964, 2025). "The results of this investigation are expected to shed light on how bone marrow–resident supporting cells contribute to osteoclastogenesis in autoimmune diseases such as rheumatoid arthritis, in which TNFα plays a central role in pathological bone destruction." (PMID 40688496, 2025). "TNFα plays a pivotal role in the progression of rheumatoid arthritis, contributing to both synovial inflammation and joint destruction." (PMID 40688496, 2025). "Inflammatory cytokines, such as IL-6 and TNF-α, can stimulate ongoing neutrophil production in rheumatoid arthritis and inflammatory bowel disease." (PMID 40149573, 2025). "TNF inhibitors (infliximab, adalimumab, etanercept) are used in treating autoimmune diseases like rheumatoid arthritis, Crohn’s disease, ulcerative colitis, psoriasis, and ankylosing spondylitis." (PMID 40362303, 2025). "RF and/or anti-CCP positivity has been identified in several studies to be associated with enhanced treatment effectiveness of rituximab, abatacept, and TNF-α inhibitors in patients with rheumatoid arthritis." (PMID 40224626, 2025). "The R4RA study, a Phase IV clinical trial, focused on patients with rheumatoid arthritis who had previously demonstrated an inadequate response to TNF inhibitors." (PMID 40269471, 2025). "TNF-α plays a key role in the pathophysiology of several autoimmune diseases, including rheumatoid arthritis and chronic low back pain." (PMID 40430212, 2025). "It reduces circulating activated granulocytes and monocytes, leading to decreased pro-inflammatory cytokines such as TNF-α and IL-1, as demonstrated in rheumatoid arthritis, psoriasis, and pyoderma gangrenosum." (PMID 41044647, 2025). "Recently, the Oral Rheumatoid Arthritis Trial (ORAL) Surveillance showed a higher risk of MACEs in patients with tofacitinib, a JAK inhibitor, compared to those with TNF inhibitor." (PMID 40943434, 2025). "Using a mouse model overexpressing TNFα we identified significant impacts on the development of craniofacial skeleton as well as the rheumatoid arthritis (RA)-affected joints, and the ascending ramus." (PMID 40140815, 2025). "In disease, they drive pathology (e.g., TNF-α in rheumatoid arthritis) and can serve as therapeutic targets (e.g., anti-TNF mAbs) or diagnostic markers (e.g., CRP)." (PMID 41007639, 2025). "The marked reduction in TNF-α and IL-6 is particularly noteworthy, as these cytokines are central to the pathology of chronic inflammatory diseases such as endometriosis, rheumatoid arthritis (RA), and inflammatory bowel disease (IBD)." (PMID 40958911, 2025). "One of the best-known decoy receptors used in the clinic is etanercept, a dimerized form of soluble TNF-RII conjugated to human IgG1, that can bind with high affinity to TNFα and effectively treat rheumatoid arthritis." (PMID 40055831, 2025). "Background as to why the study was undertaken: The development of rheumatoid arthritis (RA) involves various proinflammatory cytokines, with TNF-α being the most prominent." (PMID 40982617, 2025). "Tumor necrosis factor (TNF) inhibitors are widely used biologics in the management of rheumatoid arthritis (RA), but they can occasionally induce paradoxical inflammatory manifestations." (PMID 40385904, 2025). "KEGG analyses demonstrated that these GMRDEGs were related to rheumatoid arthritis, tumor necrosis factor (TNF) signaling pathway, amoebiasis, and others." (PMID 40933575, 2025). "Here, we propose the aspartate–TNF‐α biogenesis mechanism that results in a TNF‐α hypersecreting phenotype in rheumatoid arthritis patients also explains in part the inflammatory differences between rural and urban areas in sub‐Saharan Africa." (PMID 40489164, 2025).